BLZF1 (basic leucine zipper nuclear factor 1)
Description:
Required for normal Golgi structure and for protein transport from the endoplasmic reticulum (ER) through the Golgi apparatus to the cell surface.
Synonyms: JEM1; JEM-1; GOLGIN-45; JEM-1s
Tractability: PROTAC: UniProt records ubiquitination sites on it; ubiquitination databases record sites on it; its protein half-life has been measured.
Gene: Protein-coding gene on chromosome 1 (169,367,970 to 169,396,540, forward strand). Ensembl gene ENSG00000117475.
Subcellular location: Golgi apparatus membrane; Nucleus (Isoform 1); Cytoplasm (Isoform 2)
Subcellular location (Human Protein Atlas): Golgi apparatus; Nucleoplasm
Pathways (Reactome):
Cell Cycle: Golgi Cisternae Pericentriolar Stack Reorganization
Gene Ontology:
Molecular function: enzyme binding; protein binding; ubiquitin protein ligase binding
Biological process: Golgi organization; Golgi to plasma membrane protein transport
Cellular component: Golgi apparatus; Golgi membrane; nucleoplasm; nucleus; cis-Golgi network; cytoplasm
Genetic constraint (gnomAD): Loss-of-function variants: 37 observed, 42.52 expected, observed/expected ratio (o/e) 0.87, 90% interval 0.67 to 1.14. The upper end of that interval is the gene's LOEUF score, 1.14, which puts it in group 5 of 6, group 1 being the genes least tolerant of losing a copy. Missense variants: 437 observed, 482.19 expected, observed/expected ratio (o/e) 0.91, 90% interval 0.84 to 0.98. Synonymous variants: 133 observed, 166.47 expected, observed/expected ratio (o/e) 0.8, 90% interval 0.69 to 0.92.
Homologues: Orthologues: macaque BLZF1 (98% identical), chimpanzee BLZF1 (98% identical), dog BLZF1 (88% identical), pig BLZF1 (87% identical), guinea pig BLZF1 (87% identical), rabbit BLZF1 (86% identical), mouse Blzf1 (83% identical), rat Blzf1 (81% identical), tropical clawed frog blzf1 (66% identical), zebrafish blzf1 (58% identical), Drosophila melanogaster CG9356 (25% identical), Caenorhabditis elegans R12B2.2 (16% identical).
Diseases named in the same sentence as BLZF1 in open-access papers:
BLZF1 is named in the same sentence as 9 diseases in open-access papers, as found by Europe PMC text mining. Sharing a sentence is not in itself a finding about the gene and the disease. The quoted sentences say what the papers report.
leukemia (2 papers, 2023 to 2024). A malignant (clonal) hematologic disorder, involving hematopoietic stem cells and characterized by the presence of primitive or atypical myeloid or lymphoid cells in the bone marrow and the blood. "Western blot was performed on ten Golgi proteins (GBF1, GM130, Golgin97, TGN38, GRASP65, GRASP55, BLZF1, STX3, STX6, and GOLPH3) in small-cell lung cancer (SCLC), leukemia, colon cancer, and GIST cell lines expressing WT-KIT or MT-KIT." (PMID 37704840, 2023).
tumor (3 papers, 2014 to 2022). "It has been indicated that the newly identified RNF146 substrates basic leucine zipper nuclear factor 1 (BLZF1) and cancer susceptibility candidate 3 (CASC3) are involved in tumor development and cell proliferation." (PMID 24454854, 2014). "Treatment of EBV+ tumor cells-inoculated mice with rBCG::hGM-CSF-BZLF1 significantly delayed tumor formation and prolonged mouse survival compared to treatment with pBCG, rBCG::hGM-CSF or rBCG::BLZF1, most likely through the induction of cytotoxic T lymphocytes." (PMID 35632582, 2022).
infection (1 paper, 2022). The state of being infected such as from the introduction of a foreign agent such as serum, vaccine, antigenic substance or organism. "The derived immortalized LCL cells were then subjected to RT-qPCR to evaluate TGFBI mRNA expression levels as well as the expression of the viral genes LMP1 and BLZF1 (to assess the infection status in the presence of AFB1)." (PMID 35267594, 2022).
BLZF1 also shares sentences with these, for which no sentence is quoted: Arrhythmia (1 paper); cancer (1); cardiac conduction disorder (1); colon cancer (1); gastrointestinal stromal tumor (1); promyelocytic leukemia (1).